CCND1 (cyclin D1)
Diseases named in the same sentence as CCND1 in open-access papers (continued):
Sharing a sentence is not in itself a finding about the gene and the disease.
tumor (continued). "GSK3β is involved in tumor formation and progression and has been suggested as a tumor suppressor because its activation accelerates the degradation of oncogenes such as β-catenin, cyclin D1, and c-Myc." (PMID 35606353, 2022). "For example, the overexpression of Gli1, a key protein in the Hh pathway, is considered as a symbol of Hh pathway activation and is able to activate oncogene target genes such as Cyclin-D1, Myc, Bcl-2, Ang1/2, Snai1, Nanog, and Sox2 to promote carcinogenesis and tumour development." (PMID 36358596, 2022). "The decreasing level of β-catenin and cyclin D1 could explain that sFzd7 regulates tumor cell growth in the β-catenin-dependent pathway." (PMID 35655594, 2022). "Cyclin D1 and Slug are known to mediate tumor proliferation, metastasis and drug resistance." (PMID 36476988, 2022). "Nuclear ERα could raise the expression of CCND1 (cell cycle–related protein), which will weaken the inhibition of anticancer drugs on the proliferation of tumor cells." (PMID 35847887, 2022). "Importantly, Cyclin D1 is a key component of the MicroRNAs in the Cancer Pathway, and it controls chemoresistance and glycolysis in human tumor cells." (PMID 35712514, 2022). "Such pathway-specific measurements can be taken simultaneously with markers of tumor cell proliferation (cyclin D1, Ki67) or tumor growth [via fludeoxyglucose (18F) measured by PET/CT] to determine first if the drug is hitting its primary target and second if the drug is mediating tumor suppression." (PMID 34737704, 2021). "The results showed that ACE treatment could significantly reduce expressions of Cyclin D1 and C-myc of tumour tissues both in protein and mRNA level." (PMID 34531745, 2021). "Previously, we reported that Tspan5 is downregulated in gastric cancer tissues and functions as a tumour suppressor in stomach to control the tumour growth by regulation of cell cycle transition from G1‐S phase via decreasing the expression of cyclin D1, CDK4, pRB and E2F1." (PMID 33955149, 2021). "The mechanism underlying tumor promotion involves the mediation of the cell cycle promotion rather than mitosis, as cyclin D1, but not cyclin B1, was decreased in HCT116, SUIT-2 and OE33 cells by the downregulation of SNRPE." (PMID 34202873, 2021). "The low level of HOXB8 reduced the OS of ccRCC; however, we found that HOXB8 may also control tumor invasion by inhibiting CCND1 and MYC in the Wnt signaling pathway." (PMID 34306077, 2021). "Because of the constant overexpression of SYCP2, MYB and underexpression of CAV1 in HNSCC, these may be considered potential biomarkers of neoplasms associated to HPV, in addition to p16 and CCND1." (PMID 34830760, 2021). "It has been reported that cyclin D1 not only regulates the transition from G1 to S phase but also promotes tumor invasion and metastasis, and cyclin D1 deletion can reduce the migration of tumor cells." (PMID 34583719, 2021). "The high expression of CCND1 in ES has been demonstrated in several studies, and overexpression of this gene contributes to the dysregulation of the cell cycle in cancer, leading to the proliferation of tumor cells." (PMID 34899858, 2021). "Besides, the overexpression of cyclin D1 was found to be involved in HCC tumor cell differentiation, therefore targeting cyclin D1, is regarded as an alternative approach in cancer therapy." (PMID 34049576, 2021).
tumor (continued). "However, further research investigating the associations of IRF4 rs12203592, CCND1 rs1485993, TERT rs2242652, and MX2 rs45430 with underlying biologic pathways related to tumor progression is warranted." (PMID 34898573, 2021). "Notably, the expression of WT1 and cyclin D1 was also retained in those cases in which the conventional tumor markers (myogenin, desmin and MyoD1 for RMS; CD99 for EWS; NB84 for NB) were focally expressed or more rarely absent." (PMID 34943491, 2021). "Moreover, the protein levels of ki67, Cyclin D1, cleaved-caspase 3, and caspase 3 were examined in tumor tissues." (PMID 34805140, 2021). "Analysis of tumor DNA identified a genomic CCND1 amplification." (PMID 33466719, 2021). "CCND1 is expressed in all tumor clusters with more seen in Tr1 and Tr4." (PMID 34497364, 2021). "Western blot data showed that the HDSB11 administration inhibited NLRP3 and cyclin D1 protein expressions compared with the model group in tumor tissues and suppressed NLRP3, procaspase-1, and caspase-1 (p10) expressions compared with the control group in cells." (PMID 34239588, 2021). "It will be also of interest to determine whether this function of cyclin D1 contributes to oncogenesis and tumor development." (PMID 34335935, 2021). "CCND1 variation is frequently observed during tumor process." (PMID 33430855, 2021). "Cyclin D1 is a major cell cycle regulator and a well-known oncogene in distinct tumor entities." (PMID 34001852, 2021). "Furthermore, PBMF treatment notably upregulated the mRNA expression levels of GSK-3β, E-cadherin, Bax, Caspase-3, and Caspase-9 but substantially downregulated those of β-catenin, N-cadherin, MMP-2, MMP-9, Snail, and Cyclin D1 in tumor tissues." (PMID 33964908, 2021). "It has also been reported that prodigiosin inhibits the phosphorylation of GSK‐3β, restraining β‐catenin‐mediated Wnt activation and subsequent transcriptional activation of prosurvival genes, such as cyclin D1, slowing tumor progression in a breast cancer tumor model mice." (PMID 33841802, 2021). "Ki-67 and Cyclin D1 showed variations in expression levels in the same tumor." (PMID 34394279, 2021). "Moreover, it was found that BCAR3 activates the CCND1 promoter and CCND1 is believed to be an important tumor promotor in HNSCC that drives cells through the G1–S checkpoint of the cell cycle and contributes to unscheduled DNA replication." (PMID 34707118, 2021). "Furthermore, a statistically significant reduction (22%) in the tumor cyclin D1 expression was observed in this trial." (PMID 34362338, 2021). "In this regard, a study over 514 ALM samples identified that these tumours frequently display a dysregulated CDK4 pathway, a product of either gains of CDK4/CCND1 or loss of CDKN2A that, in turn, promote G1 to S cell cycle transition and thus contribute to tumour proliferation." (PMID 32330367, 2021). "We inferred some copy number gains of CCND1 on chromosome 11, which may contribute to its overexpression in some tumor cells in addition to transcriptional regulation mediated by ELF3." (PMID 33144684, 2021). "The results of these studies indicated that CCND1 expression levels could influence the growth of tumor cells in NSCLC." (PMID 34445227, 2021). "In addition, the positive rate of cyclin D1 was significantly higher in tumor tissues of the P+ group (30.81% ± 6.33%), approximately 2.5 times that of the control group (11.69% ± 3.58%) (p < 0.05)." (PMID 34660289, 2021). "Western blot analysis further confirmed that the upregulation of circPSMA1 might increase the expression of Akt1, cyclin D1, and β-catenin but suppress the expression of Bax in xenograft tumor tissues." (PMID 33911067, 2021). "The expression of miR‐107, E2F1, and CCND1 in the tumor tissues was examined." (PMID 34758200, 2021).
tumor (continued). "We performed DNA methylation analysis of the encoding genes FGFR1, FGFR2, FGFR3, FGFR4, FGF1-14, FGF16-23, and CCND1 at single CpG site resolution (840 CpG sites) employing The Cancer Genome Research Atlas (TCGA) HNSCC cohort comprising N = 530 tumor tissue and N = 50 normal adjacent tissue samples." (PMID 34933671, 2021). "Moreover, CK, Rg5, and Rk1 suppressed tumor growth in mice xenograft models by inhibiting cyclin D1, phosphatidylinositol-3-kinase (PI3K)/Akt, and reactive oxygen species (ROS)/PI3K/Akt signaling pathway, respectively." (PMID 33623532, 2021). "Cyclin D1 plays a vital role in cell cycle progression and tumor progression." (PMID 34224316, 2021). "FAK plays a role in the regulation of cell cycle progression, correlating with changes in cyclin D1 expression, and cyclin D1 deregulation may promote tumor development." (PMID 33726836, 2021). "It was also demonstrated that a CCND1 amplification and/or loss of p16 in the primary tumour did not improve the efficacy of therapy." (PMID 34068388, 2021). "Additionally, we inspected the p-Akt (Ser473), p-GSK-3β(Ser9), Snail, E-cadherin, N-cadherin and Cyclin D1 contents in HCC tumor tissues using IHC." (PMID 33762939, 2021). "In addition, the mRNA level of genes ZEB1, Cyclin D1 and Survivin related to tumor prognosis were also significantly down-regulated." (PMID 34095137, 2021). "All tumor components showed nuclear expression of β-catenin and cyclin D1." (PMID 34513702, 2021). "Moreover, they investigated the role of this gene in mice models and observed that RAB3A affects tumour initiation, transformation and drug-resistance primarily by inducing cell cycle progression through cyclin D1 stimulation." (PMID 33686173, 2021). "We found that in most cases, p16 showed a loss of expression in cartilage and dedifferentiated components, which may suggest that the inhibition of CDK4 and Cyclin D1 was reduced, prompting tumor cells to enter the cell cycle progression." (PMID 34631758, 2021). "Interestingly, Ccne1-depleted tumours also displayed reduced levels of Ccnd1 and Ccna2 compared to WT mice." (PMID 34830835, 2021). "However, for tumoral cells to gain an invasive capacity, cell cycle arrest is required, which depends on the decrease of cyclin D1 and Ki-67 in the front of tumor." (PMID 34071030, 2021). "In addition, cell cycle–related proteins, including CDK4/CDK6 and cyclin D1 were up-regulated upon tumor onset in thymi harboring small tumors, which was maintained in end-stage tumors for most of the samples tested." (PMID 33310759, 2021). "Furthermore, PTL was proven to inhibit the tumor promoter-induced NF-κB activity and modulate p21 and cyclin D1 NF-κB target genes, and also inhibit the TPA-induced tumor growth in vivo." (PMID 34835969, 2021). "Moreover, siRNA-mediated STAT3 inhibition reduced the total protein levels of tumor-promoting genes Mcl1, Cyclin D1, VEGF, and Bcl-XL, suggesting that STAT3 is required for proliferation and survival in Olaparib-resistant cells." (PMID 34956861, 2021). "Moreover, parafibromin activates Wnt signaling by directly interacting with β-catenin and suppresses tumor growth via the down-regulation of cyclin D1 expression, inhibiting the G1 to S phase transition of the cell cycle and inducing apoptosis of tumor cell." (PMID 34681865, 2021). "Additionally, INT-1B3 treatment decreased tumor CCND1 mRNA expression by 43% relative to PBS-treated tumors." (PMID 33747358, 2021). "Upon disease progression, we used a targeted systemic approach based on the whole genomic profile of the primary tumor, which showed PTEN loss, which is predictive of a benefit from an mTOR inhibitor, and a CCND1 amplification, which predicts sensitivity to CDK4/6 inhibitors." (PMID 34829431, 2021).
tumor (continued). "As an oncogene, CCND1 was shown to promote tumor growth by regulating cyclin-dependent kinase 4 (CDK4), through modulating the cell cycle transtion from the G1 to the S phase, thereby making CCND1 and its regulatory partner, CDK4, attractive potential therapeutic targets." (PMID 34063946, 2021). "The inhibitory effect of ELF5 on tumor proliferation was abolished in a CCND1 rescue experiment or by overexpression of Cyclin D1, suggesting that the function of ELF5 might be CCND1-dependent." (PMID 33742100, 2021). "In addition, we performed immunofluorescence staining in the tumour tissue sections of xenograft mice and found that cyclin D1 expression was dramatically inhibited in the METTL16 knocked down group." (PMID 34075693, 2021). "Lower Cyclin D1 level was found to correspond to higher ELF5 expression in tumor tissues." (PMID 33742100, 2021). "Therefore, CCND1 has attracted extensive and in-depth attention and research in the field of tumor research." (PMID 34294689, 2021). "Interestingly, further recent data report that Cyclin D1 induces the secretion of specific miRNAs governing the tumor immune response." (PMID 33317149, 2020). "One patient had a CCND1 copy number gain in a HER2‐negative invasive tumour component." (PMID 32058674, 2020). "Another possibility is that CCND1 protein itself may function as a tumor antigen recognized by T cells." (PMID 33299117, 2020). "Analysis of expression changes between paired tumor and normal samples revealed that expression of the CCND1 gene is upregulated mainly in HPV(−) patients, and, unexpectedly, it may also be downregulated, predominantly in HPV(+) patients." (PMID 32224897, 2020). "Our results demonstrate that the addition of CITCO to the CHOP regimen leads to significant suppression of the growth of EL-4 xenografts in hCAR-transgenic mice accompanied by reduced expression of cyclin-D1, ki67, Pcna, and increased caspase 3 fragmentation in tumor tissues." (PMID 33233444, 2020). "Several studies have revealed that UGR4 could control the proliferation and cell cycle progression of tumor cells by regulating cyclin D1." (PMID 32552851, 2020). "Studies have shown that metformin inhibits the invasion and metastasis of tumor cells and induces degradation of cyclin D1 through AMP-activated protein kinase/glycogen synthase kinase 3 beta (AMPK/GSK3β) signaling axis to participate in the protein ubiquitination process." (PMID 32631421, 2020). "In Apc-deficient PSCC, Sox2 may collaborate with β-catenin to regulate the pro-tumor transcriptome, such as upregulation of cyclin D1 in breast cancer." (PMID 32358507, 2020). "Furthermore, combination treatment alone restored β‐catenin and the well‐characterized β‐catenin target gene cyclin D1 (CCND1) expression to tumor‐free control levels." (PMID 31930715, 2020). "Previously, we detected cyclin D1 overexpression in more than 90% of NPC tumor tissues." (PMID 33243298, 2020). "Microscopically, the tumor cells were strongly positive for Desmin, Cyclin D1 and WT1, moderately positive for ER/PR, weakly positive for SMA (smooth muscle actin) and negative for CD 10, and the expert pathologist concluded it was “ESS with smooth muscle cells differentiation”." (PMID 32933053, 2020). "Another potential marker of tumour cell proliferation is cyclin D1." (PMID 32374893, 2020).
tumor (continued). "Also, Cyclin D1 can also be used as indicative for PC progression and predicting tumor cells invasion to perineural tissues." (PMID 32552908, 2020). "Cyclin D1 is a major cell cycle regulator for both normal and tumour cells." (PMID 33174391, 2020). "The second point suggests that CCND1 expression in tumor cells might be a good target for T cells reactivated by ICIs." (PMID 33299117, 2020). "The findings in some of these studies have additionally suggested that ZKSCAN3 could modulate several molecules known to play a key role in tumorigenesis and/or tumor progression, such as cyclin D1/D2, EGF, IGF-2, integrin-β4, MMP2/MMP9, NF-κB, and VEGF." (PMID 32824199, 2020). "In both ways, overexpression of CCND1 results in a shorter cell cycle and tumor progression." (PMID 32566661, 2020). "The immunohistochemical analysis showed that the FD extract had significantly decreased the expression of the key tumor marker cyclin D1 and had significantly increased the expression of the β-catenin and e-cadherin antibodies that are associated with enhanced cellular adhesion." (PMID 32104177, 2020). "Furthermore, western blot results indicated that β-catenin, P-AKT,P-GSK-3β, Cyclin D1, Vimentin, and Bcl-2 protein expression in xenograft tumor were obviously reduced in SC66 treatment group." (PMID 32848734, 2020). "Similarly expression of Ki- 67 and Cyclin D1 in metastastic tumours was also insignificant (p= 0.44 and 0.99 respectively) when compared in the sites of involvement." (PMID 31983161, 2020). "Extracted from another famous herbal medicine named Curcuma longa L., curcumin (25 mg/kg/day for 62 days) promoted the accumulation of cells in G0/G1 phase and subsequently induced tumor cell apoptosis by regulating targets that involved WNT/β-catenin like cyclin D1 in AOM/DSS-challenged mice." (PMID 32410986, 2020). "Moreover, c-Myc is an important transcription factor that promotes the expression of cyclin D1 during cell proliferation and tumor development." (PMID 33134174, 2020). "Based on these findings, we hypothesized that GOLPH3 associated with STIP1 might regulate hTERT and telomerase activity via c-Myc, and then regulate cyclin D1 to promote the division and proliferation of tumor cells." (PMID 33134174, 2020). "Notably, Cyclin D1 overexpression is a fundamental determinant of the reciprocal interplay between cancer cells and the stroma, exerting in such a way a “tumor-promoting” action." (PMID 33317149, 2020). "Furthermore, cyclin D1 acts as an oncogene, which profoundly affects the tumor microenvironment promoting tumor metastasis and increasing angiogenesis." (PMID 32697404, 2020). "The main function of cyclin D1 is to promote cell proliferation by regulating the cell cycle, which is closely related to the occurrence of tumors and is a marker of proliferation of tumor cells (including ccRCC)." (PMID 32164618, 2020). "Herein, we found that ASPM ablation reduced the expression levels of CCND1 and CDK4, which may cause the disorder of LSCC cell cycle and further block cell proliferation and tumor development." (PMID 32742488, 2020). "Similarly, microRNA-623 targeting of cyclin D1 also makes GC tumor cells more sensitive to 5-fluorouracil, thus improving the therapeutic effect of drugs." (PMID 32090087, 2020). "However, the coexpression of cyclin D1 and p21 protein is required for the initial steps of tumor development." (PMID 32405344, 2020). "Therefore, the full implication of Cyclin D1 in the molecular connection between tumor and stroma deserves more complete investigation regarding the mechanism of CCND1 amplification and primary immune resistance." (PMID 33317149, 2020). "In patient 1, CCND1 amplification was identified solely in tumour #1." (PMID 31929516, 2020).